ZNF385B (zinc finger protein 385B)
Synonyms: ZNF533; FLJ25270
Tractability: No criterion of Open Targets' tractability assessment is met for any kind of drug.
Gene: Protein-coding gene on chromosome 2 (179,441,982 to 179,861,612, reverse strand). Ensembl gene ENSG00000144331.
Subcellular location: Nucleus
Subcellular location (Human Protein Atlas): Nucleoli fibrillar center
Gene Ontology:
Molecular function: nucleic acid binding; zinc ion binding
Cellular component: fibrillar center; nucleus
Genetic constraint (gnomAD): Loss-of-function variants: 20 observed, 38.68 expected, observed/expected ratio (o/e) 0.52, 90% interval 0.36 to 0.75. The upper end of that interval is the gene's LOEUF score, 0.75, which puts it in group 3 of 6, group 1 being the genes least tolerant of losing a copy. Missense variants: 515 observed, 581.69 expected, observed/expected ratio (o/e) 0.89, 90% interval 0.82 to 0.95. Synonymous variants: 191 observed, 218.58 expected, observed/expected ratio (o/e) 0.87, 90% interval 0.78 to 0.99.
Homologues: Orthologues: macaque ZNF385B (99% identical), chimpanzee ZNF385B (97% identical), pig ZNF385B (95% identical), dog ZNF385B (95% identical), guinea pig ZNF385B (92% identical), mouse Zfp385b (90% identical), rat Zfp385b (90% identical), rabbit ZNF385B (78% identical), tropical clawed frog znf385b (75% identical), zebrafish znf385b (63% identical), Drosophila melanogaster dbf (23% identical), Drosophila melanogaster CG1231 (16% identical). Paralogues in human: ZNF385D (48% identical), ZNF385C (40% identical), ZNF385A (36% identical), ZMAT1 (14% identical), ZMAT3 (13% identical), ZMAT4 (11% identical), ZNF346 (11% identical), ZMAT2 (9% identical), KRCC1 (5% identical).
Diseases named in the same sentence as ZNF385B in open-access papers:
ZNF385B is named in the same sentence as 23 diseases in open-access papers, as found by Europe PMC text mining. Sharing a sentence is not in itself a finding about the gene and the disease. The quoted sentences say what the papers report.
breast carcinoma (4 papers, 2010 to 2021). "Although numerous studies have demonstrated the potential function of zinc finger proteins in tumor progression, the effects of ZNF385B in breast cancer (BC) are less studied." (PMID 33614780, 2021). "Eight of these 29 (28%) CNV loci were confirmed by qPCR and/or Nanostring analysis, including four loci that were associated with breast cancer (GTF2H2, ZNF385B, NAALADL2 and PSG5) and two loci that were associated with ovarian cancer (CYP2A7 and OR2A1)." (PMID 28145423, 2017). "These include four loci that were associated (unadjusted P<0.05) with breast cancer (GTF2H2, ZNF385B, NAALADL2 and PSG5), and two loci associated with ovarian cancer (CYP2A7 and OR2A1)." (PMID 28145423, 2017). "Among the listed genes, BIRC5, SEC14L2, Thymidine kinase (TK1), ZNF385B, CLIC6, ELOVL1, CHAF1B and TFF1 have been reported to have a role in early detection of cancers, tumor progression and metastasis in most of cancer types including breast cancer." (PMID 31703592, 2019).
Obesity (3 papers, 2012 to 2024). Accumulation of substantial excess body fat. "Navigating syntenic regions suggests obesity candidate genes on chromosome 2 that are previously known to be associated with obesity-related diseases: MRPL33, PARD3B, ERBB4, STK39, and ZNF385B." (PMID 23253381, 2012). "ZNF385B is implied as a candidate gene for obesity in humans and pigs." (PMID 38254476, 2024).
ovarian carcinoma (2 papers, 2012 to 2017). A malignant neoplasm originating from the surface ovarian epithelium. "The present study is to our knowledge the first to link ZNF385B to ovarian cancer." (PMID 23029477, 2012).
brain cancer (1 paper, 2021). A primary or metastatic malignant neoplasm affecting the brain. "Then, single gene analysis was performed in pan-cancer about ZNF385B using the web-based tool “ESurv”, and it was found that aberrant expression of ZNF385B was related to poor prognosis of BC, renal cancer, liver cancer, and brain cancer." (PMID 33614780, 2021). "Firstly, the Oncomine database was used to assess the differential expression of ZNF385B mRNA levels in various cancers, and low ZNF385B expression was found in multiple types of cancer, such as BC, brain malignant tumor, lung cancer, kidney cancer, and liver cancer." (PMID 33614780, 2021).
bronchopulmonary dysplasia (1 paper, 2022). Bronchopulmonary dysplasia is a chronic respiratory disease that results from complications related to lung injury during the treatment of infant acute respiratory distress syndrome in low-birth-weight premature infants or from abnormal lung development in older infants. "miR-1258 is located in the first intron of its host gene ZNF385B (Zinc Finger Protein 385B) on chromosome 2q31.3 and plays a key regulatory role in intestinal barrier function, herpesvirus Lytic replication, bronchopulmonary dysplasia, brown adipose differentiation, and other diseases." (PMID 36249037, 2022).
Burkitt lymphoma (1 paper, 2021). A rare form of malignant mature B-cell non-Hodgkin lymphoma. "In addition, ZNF385B is expressed only in Burkitt lymphoma cells, but hardly in diffuse large B-cell lymphoma." (PMID 33614780, 2021).
ductal carcinoma in situ (1 paper, 2021). "The validation via the microarray GSE21422 demonstrated that ZNF385B expression levels in tumor tissues, which included invasive ductal carcinoma (ICD) and ductal carcinoma in situ (DCIS), were lower than those in healthy samples (p = 0.03)." (PMID 33614780, 2021).
infiltrating ductal carcinoma (1 paper, 2021). "Furthermore, low ZNF385B expression significantly affected the OS in infiltrating ductal carcinoma (p = 0.00031), ER-negative BC (p = 0.04), ER-positive BC (p = 0.0025), PR-negative BC (p = 0.00015), HER-2-negative BC (p = 0.0038), and HER-2-positive BC (p = 0.0013) through subgroup analysis." (PMID 33614780, 2021).
ovarian tumour (1 paper, 2012). "ZNF385B, previously unrecognized as a potential ovarian tumour marker, and VEGFA correlated with overall and progression-free survival, respectively, whereas TPX2 and FOXM1 with optimal CA125 normalization." (PMID 23029477, 2012).
tumor (6 papers, 2012 to 2025). "The tumor suppressor miR-1258, which targets PD-L1, is under transcriptional control of its host gene ZNF385B." (PMID 37239435, 2023). "This miRNA is silenced and methylated in a tumor-specific manner in myeloma, with an inverse correlation between methylation status and expression of ZNF385B/miR-1258." (PMID 37239435, 2023). "Thus, when the transcriptional inhibition of ZNF385B decreases and mRNA levels increase, tumour growth/metastasis is promoted, resulting in shorter OS." (PMID 23029477, 2012). "Thus, tumor growth and metastasis could be promoted when the transcriptional repression of ZNF385B reduced and mRNA levels raised and resulted in shorter OS." (PMID 33614780, 2021). "Top hits include changes in transcriptional regulation (ZNF385B, SNORA65), tumour microenvironment (COL1A2, COL3A1), and metastatic processes (UCHL1, SUCNR1, THY1)." (PMID 40890143, 2025). "By comparing expression levels of 16 genes between 779 BRCA samples and 100 paired normal breast tissues, 7 genes expression, such as C7orf63, C9orf103, IGJ, ZNF385B and TNN, was significantly lower in tumor tissues as compared with those in normal tissues." (PMID 35853971, 2022).
cancer (2 papers, 2019 to 2021). A tumor composed of atypical neoplastic, often pleomorphic cells that invade other tissues. "In the present research, we found differential expression of ZNF385B in multiple types of cancer including BC compared to normal tissues using the Oncomine database and significant prognostic value of ZNF385B in BC based on a web-based tool “ESurv”." (PMID 33614780, 2021). "The Oncomine database and “ESurv” tool were used to explore the differential expression of ZNF385B in pan-cancer." (PMID 33614780, 2021). "ZNF385B expression was downregulated in most types of cancer including BC." (PMID 33614780, 2021).
cardiac disease (1 paper, 2024). "Regarding the miRNA–mRNA pairs, miR-125a-5p/NIPAL4, miR-135a-5p/ZNF385B, miR-140-3p/FKBP3, miR-140-3p/SKP1 and miR-140-3p/NDUFA4, very little or nothing is known about the function of these genes in cardiac disease." (PMID 39200271, 2024).
ZNF385B also shares sentences with these, for which no sentence is quoted: Serous Ovarian Carcinomas (2 papers); Anorexia (1); autism (1); cardiovascular disease (1); diffuse large B-cell lymphoma (1); kidney cancer (1); liver cancer (1); lung carcinoma (1); orofacial cleft (1); renal carcinoma (1); sudden cardiac arrest (1).